ALB (albumin)
Diseases named in the same sentence as ALB in open-access papers (continued):
Sharing a sentence is not in itself a finding about the gene and the disease.
diabetes (continued). "The predictive power of IS for all-cause mortality was independent of age, gender, diabetes mellitus, albumin, hemoglobin, phosphate, and aortic calcification." (PMID 38184721, 2024). "Furthermore, albumin also played an essential role in various inflammatory diseases, such as ST-elevation myocardial infarction, coronary artery disease, and diabetes." (PMID 39722824, 2024). "The dimensionality was reduced to 15 features after LASSO, including preoperative fever, ASA, PT, hsCRP, BUN, diabetes, duration of surgery, ulinastatin, methylprednisolone, alanine aminotransferase, total volume of fluid loss, volume of blood loss, DBILI, albumin, and gender." (PMID 39501984, 2024). "Through these sensitivity analyses, we affirmed the significant impact of BMI ≥24 kg/m2, diabetes, preoperative low albumin levels, preoperative malnutrition, operations exceeding 3 h, and laparoscopic surgery on the risk of postoperative incision infections in colorectal cancer patients." (PMID 39193402, 2024). "In this study, 15 variables were identified to be significantly associated with postoperative SIRS, including preoperative fever, ASA, PT, hsCRP, BUN, diabetes, duration of surgery, ulinastatin, methylprednisolone, ALT, total volume of fluid loss, volume of blood loss, DBILI, albumin, and gender." (PMID 39501984, 2024). "Albumin changes were associated with all-cause death and cardiac death among participants with male, age ≥ 75, hypertension, non-diabetes, congestive heart failure, non- PVD, and non-stroke." (PMID 39902029, 2024). "Indeed, in conventional PD, diabetes mellitus and low serum albumin levels are becoming predicting factors for complications and poor prognosis that need to be considered before the initiation of conventional PD." (PMID 39135880, 2024). "Several mechanisms may explain the link between albumin levels and the incidence of diabetes and its complications." (PMID 39796544, 2024). "Notably, the vaccinated group exhibited a shorter diabetes history, lower mean systolic blood pressure, and higher hemoglobin, albumin, serum iron, and estimated glomerular filtration rate (eGFR) levels compared to the unvaccinated group." (PMID 39228893, 2024). "The adrenal thickness is independently associated with BMI, WC, cortisol levels, urinary albumin/creatinine ratio, hypertension, and dyslipidemia but not glycemic parameters in patients with diabetes." (PMID 37751894, 2024). "Albumin changes were associated with gastrointestinal hemorrhage among patients with male, age ≥ 75, BMI < 25 or ≥ 25, smoker or not, hypertension, non-diabetes, congestive heart failure or not, PVD, and stroke or not." (PMID 39902029, 2024). "A low serum albumin level may be used as an index of poor nutritional status and most commonly occurs in older, obese, and diabetes patients." (PMID 39766057, 2024). "Age, gender, vigorous PA, smoking status, alcohol consumption, diabetes status, eGFR, serum albumin level, uric acid level, and blood urea nitrogen level were identified as factors associated independently with mortality in the Cox proportional hazards analysis." (PMID 39482632, 2024). "Urine albumin levels correlated positively with diabetes control according to HbA1c levels." (PMID 39597886, 2024). "Logistic regression analysis showed that systolic blood pressure, diastolic blood pressure, course of diabetes, fasting blood glucose (FBG), two hours postprandial blood glucose (two hours PBG) and urinary albumin were independent risk factors for T2DM complicated with PDR." (PMID 38545017, 2024). "Cluster B patients with diabetes with a higher risk of periodontitis were found to have higher levels of ALB and ALT, suggesting that elevated levels of ALB and ALT remain important predictive risk factors for periodontitis development in patients with diabetes." (PMID 39632553, 2024). "As expected, diabetes induced a significant increase in extravascular albumin." (PMID 39348530, 2024).
diabetes (continued). "RDW and albumin are routinely measured as part of the extensively used complete blood counts, and they would not require any additional cost, providing a simple and feasible tool for PAD risk identification in patients with diabetes." (PMID 38405142, 2024). "Maximum sedentary bouts (minutes) (β = -0.389, p = 0.001) and sedentary behavior (minutes) (β = -0.377, p = 0.001) were identified as factors affecting HRQOL after adjustments for sex, the duration of hemodialysis, age, a history of diabetes mellitus, BMI, and albumin." (PMID 39463640, 2024). "Potential improvements include integrating comprehensive immunological parameters (e.g., CD19, CD56 cell counts, and inflammatory markers), incorporating sensitive diabetes-related indicators (e.g., glycated albumin), and accounting for medication adherence and treatment history." (PMID 39866736, 2024). "Serum phosphate and hemoglobin levels were positively associated (r = 0.042, p = 0.001), and both variables were related to albumin, serum calcium, dementia, diabetes, serum bicarbonate, kT/V, COPD, malignancy, phosphate binders, serum potassium, reactive c protein, and heart failure (all p < 0.05)." (PMID 39407717, 2024). "Significant differences were observed across the quartiles of Dietary folate intake in terms of age, gender, race, marital status, Poor income ratio, body mass index (BMI), diabetes mellitus, urinary albumin-to-creatinine ratio (UACR), and glycosylated hemoglobin levels." (PMID 39040924, 2024). "However, a subsequent study showed that albumin-adjusted serum calcium was unrelated to the incidence of diabetes." (PMID 38505748, 2024). "Univariate analyses revealed associations between H. pylori seropositivity and variables such as age, sex, education, poverty-to-income ratio (PIR), body mass index (BMI), alcohol use, diabetes mellitus, serum albumin, heart failure, cardiac assault, and niacin intake." (PMID 39146291, 2024). "Interestingly, the interaction effect of OH/ECW after adjusting for age, sex, LVMI, LVEF, cDBP, cPP, and serum albumin levels for patients with diabetes was marginally significant (P = 0.062)." (PMID 38177252, 2024). "However, in the context of chronic diseases such as diabetes and dyslipidemia, which were more prevalent among our hyperalbuminemia cohort, the interpretation of elevated serum albumin levels becomes more nuanced." (PMID 39192915, 2024). "Few studies have established the connection of blood urea nitrogen/albumin (BAR) with diabetes, and its link to subsequent diabetic complications and mortality remains unclear." (PMID 39796544, 2024). "Likewise, kidney damage was more prevalent among patients with diabetes, evidenced by higher blood levels of urea, creatinine, sodium, potassium and lower of albumin." (PMID 37845766, 2023). "Das Urin-Albumin-Kreatinin-Verhältnis Erkennen eines Nierenschadens bei Typ-2-Diabetes." (PMID 37955643, 2023). "After adjusting for age, gender, body mass index, hypertension, diabetes mellitus, dialysis vintage, total cholesterol, low-density lipoprotein cholesterol, albumin, C-reaction protein, calcium, phosphorus, use of antihypertensive drugs and cholecalciferol drugs." (PMID 37779359, 2023). "Forty-four patients (5.7%) had diabetes and the median serum albumin level was 4.1 g/dL." (PMID 37120533, 2023). "And 4803 participants were finally included for analysis using the model 3, which was adjusted by age, gender, race, educational level, marital status, total energy intake, physical activity, smoking, hypertension, diabetes, urine creatinine, albumin and marihuana use." (PMID 37404817, 2023). "In addition, the Cox proportional hazard model showed that hANP was an independent prognostic marker of hospitalization due to AHF after adjusting for sex, age, hemoglobin, albumin, and history of diabetes." (PMID 36941501, 2023).
diabetes (continued). "When stratified by diabetes, serum albumin level was also higher in CKD patients with LPD–KAs compared to those with LPD alone in both diabetes (3.9 ± 0.6 vs. 3.7 ± 0.6 g/dL, p = 0.002, respectively) and non-diabetes (3.8 ± 0.5 vs. 3.6 ± 0.7 g/dL, p = 0.001, respectively)." (PMID 37726370, 2023). "The univariate logistic regression analysis showed that WBC, NEUT, AST, ALB, TC, LDL-C, Hcy, LDH, IMA, number of children, (fr)AGILE score, Na+, potassium, calcium, magnesium, albumin, blood transfusion, anti-infection, and diabetes were statistically significant in the model (p < 0.05)." (PMID 38249717, 2023). "Recipient and donor age, recipient and donor sex, type of transplantation (living or deceased donor), history of diabetes mellitus, smoking history, and laboratory tests including hemoglobin, albumin, and eGFR one year after KT were used as covariates in the multivariate Cox regression analysis." (PMID 36650247, 2023). "Another important finding in our study is the association of ferritin levels with all-cause mortality only in the group of patients without diabetes and after adjustment to age and serum albumin." (PMID 36719878, 2023). "In addition, increases in the urinary excretion of albumin and IgG induced by diabetes were more readily normalised by euglycemia." (PMID 36983632, 2023). "NFS was calculated using the following equation: NFS = −1.675 + 0.037 - age + 0.094 – body mass index +1.13 × impaired fasting glucose/diabetes mellitus +0.99 × aspartate aminotransferase/alanine aminotransferase ratio - 0.013 × platelet count - 0.66 × serum albumin." (PMID 37711740, 2023). "Diabetic rats exhibited a significant increase in serum protein, albumin, ALT, and AST levels compared to the normal control group, indicating potential liver damage and dysfunction due to the metabolic changes associated with diabetes." (PMID 37280499, 2023). "In the subgroup with normal cognitive function, patient demographics, laboratory data, and comorbidities (age, education, diabetes, hemoglobin, albumin, CRP, CAS percentage, Ccr, LVMI, and LVH percentage) were significantly different compared with the CI group." (PMID 36890445, 2023). "Regarding medical variables, the low phosphorus group had a higher percentage of diabetes, lower diastolic pressure, lower concentrations of urea, creatinine, albumin, cCa, PTH, and CRP, and higher levels of glucose, triglycerides, and residual renal function (RRF)." (PMID 37497059, 2023). "Using the LASSO regression analysis, younger age, higher BMI, no previous TB history, the presence of diabetes, and lower albumin level were significantly associated with TB disease versus NTM infection for prediction model." (PMID 38001469, 2023). "Indeed, the renal function results showed that obesity and diabetes led to albuminuria and increased albumin-to-creatinine ratio (ACR) in both male and female mice." (PMID 37091852, 2023). "Of particular interest, in diabetes and in diabetic nephropathy, metformin has been shown to induce the synthesis of ALB by primary cultured hepatocytes and to reduce albuminuria and exert a profound anti-inflammatory renoprotective role in diabetic nephropathy in vivo." (PMID 37762957, 2023). "After dividing the sample into patients with and without diabetes, we found age, hemoglobin and serum albumin significantly associated with all-cause mortality in patients without diabetes." (PMID 36719878, 2023). "Although the detection of urinary protein content is the most common screening method for nephropathy in diabetes patients, the renal injury may have lasted for a long time before the significant clinical change of urinary albumin content." (PMID 37525631, 2023). "Univariate analysis revealed that the following variables were significantly associated with infection: sex, hypertension, diabetes, smoking, drinking, primary liver cancer, alcoholic, autoimmunity, GIB, HE, HF, TP, TB, hemoglobin, Na, K, ALB, PTA, BUN, Cr, RBC count, WBC count, and NLR." (PMID 37704966, 2023).
diabetes (continued). "Some cross-sectional studies have shown that a lower HRV was significantly associated with traditional and nontraditional risk factors for CVD, including diabetes, lower albumin, and higher phosphorus, CRP, and eGFR < 15 mL/min/1.73 m2." (PMID 36832273, 2023). "Of the variables that were statistically significant in the univariate analysis, a 10-year age increase, history of diabetes or CVD, 5 g/L serum albumin decrease, and ESA treatment were significantly associated with higher CV-MACE risk in the joint final model." (PMID 37289366, 2023). "Likewise, markers of kidney damage were more prevalent among patients with diabetes, evidenced by greater blood levels of urea, creatinine, sodium, potassium and lower of albumin." (PMID 37845766, 2023). "Elevated levels of albumin could reduce the complications of diabetes, such as diabetic nephropathy, diabetic retinopathy, diabetic peripheral neuropathy, and the mortality associated with diabetes." (PMID 38111710, 2023). "The following variables were scored as 0, 1, 2, or 3 as per severity: body mass index, HD vintage in years, functional capacity, serum albumin, serum ferritin, and the number of co-morbid conditions (diabetes mellitus, hypertension, ischemic heart disease, and cerebrovascular disease)." (PMID 38299137, 2023). "Albumin is a globular protein and as a carrier protein (carrier of lipophilic substances like thyroid hormone, sex hormone, and triglycerides), it is used in the treatment of conditions like rheumatoid arthritis, diabetes, hepatitis, cancers, etc.." (PMID 37176983, 2023). "In multiple regression analysis, serum magnesium levels were independently associated with increased CFS scores (β = − 0.126, P = 0.005) adjusted for age, body mass index, diabetes, cardiovascular diseases, prevalent fractures, serum albumin and C-reactive protein." (PMID 37696942, 2023). "In conclusion, our study reveals that age, monocytes, neutrophils, serum albumin, serum potassium, cardiovascular disease, diabetes mellitus, serum creatinine, and HbA1C are all significant factors tied to the risk of all-cause mortality in individuals with hypertension." (PMID 38074152, 2023). "On a subset of propensity-score matched patients, well balanced for sex, age, dialysis vintage, diabetes, albumin, hemoglobin, Calcium, Phospahte, PTH and therapies, PTX was confirmed to be a protective factor for overall survival (HR: 0.404 [0.254–0.643]; p = 0.00132)." (PMID 37351832, 2023). "Beneficial reduction in urinary albumin excretion was demonstrated by clinical trials in diabetes." (PMID 36978832, 2023). "This study aimed to investigate the utility of carcinoembryonic antigen (CEA), C-reactive protein (CRP), serum albumin level, hemoglobin, and lactate dehydrogenase (LDH) as biomarkers for cancer risk, and the biological implications of diabetes on the evolution and prognosis of oncological patients." (PMID 37627906, 2023). "Serum albumin was the only factor associated with mortality in both groups, diabetes and no diabetes." (PMID 36719878, 2023). "Before surgery, we should pay attention to and try to improve the patient's general condition, perform transfusion, supplement albumin, carry out enteral nutrition to improve the patient's nutritional status, and actively treat basic diseases such as hypertension, heart disease, and diabetes." (PMID 36855086, 2023). "In both univariate and multivariable analyses, culture-positive peritonitis, diabetes mellitus, and albumin levels were not positively associated with the primary response." (PMID 37978358, 2023). "Univariate Cox regression analysis revealed that all-cause mortality was associated with age (p < .001), diabetes mellitus (p < .001), coronary heart disease (p = .004), HGB (p = .032), albumin (p < .001), ferritin (p = .02), PLR (p < .001), and NLR (p < .001)." (PMID 37724554, 2023).
diabetes (continued). "The highest delivered BSA-adjusted volume (>23 L per 1.73 m2 BSA per session) was associated with a 22% reduction in all-cause mortality and a reduction of 31% in cardiovascular mortality after an adjustment for age, gender, albumin, creatinine, history of CV diseases, and history of diabetes." (PMID 36829639, 2023). "The other various covariates data obtained from the NHANES questionnaire and laboratory measurements, including age, gender, education, race/ethnicity, uric acid, total serum cholesterol, albumin, Vitamin C, folate, alcohol drinking, smoking status, history of diabetes, and hypertension." (PMID 37273879, 2023). "Aware of the risks of diabetes-related complications, the patient intentionally reduced his dietary intake, resulting in poor post-operative nutritional intake and a significant decrease in his serum albumin level (33.3g/L, compared to 43.3g/L preoperatively)." (PMID 38013258, 2023). "Thus, the C-reactive protein/albumin rate is elevated in inflammatory conditions like diabetes and its microvascular complications." (PMID 37370958, 2023). "Association of PCF with variables such as age, sex, BMI, smoking, tumor grading, stage, diabetes, hypertension, anemia, preoperative hemoglobin, preoperative Albumin, closure type, previous tracheostomy, previous chemotherapy, history of radiotherapy, Neck dissection, surgical margin, Etc." (PMID 37251293, 2023). "In 2023, the ADA updated the recommendation for standards of care in patients with CKD and diabetes to recommend the use of SGLT2 inhibitors even with urinary albumin ranging from normal to 200 mg/g creatinine (Grade B recommendation) following the EMPA-KIDNEY trial." (PMID 38105902, 2023). "This study determined whether the experience of severe illness, recurrence, diabetes, history of biliary surgery, BMI, neutrophil percentage, hemoglobin, and ALB are the main influencing factors of PPC." (PMID 38013294, 2023). "On univariate analysis: age, smoker status, The European System for Cardiac Operative Risk Evaluation (EuroSCORE) II, systemic hypertension, diabetes mellitus, prior congestive heart failure (CHF), and a higher preoperative NLR, PLR, SII, and albumin were significant predictors of NOAF." (PMID 37587676, 2023). "However, years of diabetes can compromise the integrity of the blood-retina barrier, leading to increased permeation of plasma components such as ALB, carbohydrates, and lipids into the retinal environment." (PMID 37781924, 2023). "Moreover, participants with decreased serum albumin were more likely to have hypertension, failing kidneys, diabetes, stroke, asthma, emphysema, and coronary heart diseases when compared to the Q4 group." (PMID 36950094, 2023). "Through reviewing previous literatures and assessing the confounding, the final regression models were adjusted for age, PD duration, comorbidity of diabetes mellitus, serum albumin level, CRP level, fungal peritonitis, Gram-negative bacteria peritonitis, and multi-organism peritonitis." (PMID 37737145, 2023). "Conversely, the decrease in serum albumin (indirect indication of high urine ALB) associated with a decline renal function was apparent, consistent with the albumin-to-creatinine ratio as a risk factor for diabetes-related outcomes." (PMID 38089059, 2023). "Serum HbA1c, FA, albumin-corrected fructosamine (AlbF), total protein-corrected FA (PrF), hemoglobin (Hb), and hematocrit (Hct) were estimated in 32 controls (Group I) and 32 cases of diabetes mellitus (DM) (Group II)." (PMID 36779109, 2023). "In addition, eGFR, diabetes and hypertension were independent variables showing associations with the POR for albumin in women." (PMID 37755765, 2023). "They found that the PRS was associated with the incidence of de novo HCC, and that this association was independent of classical risk factors (i.e., sex, diabetes, albumin) and the severity of liver disease." (PMID 36854015, 2023).